EGFR (epidermal growth factor receptor)
Diseases named in the same sentence as EGFR in open-access papers (continued):
Sharing a sentence is not in itself a finding about the gene and the disease.
ovarian carcinoma (continued). "Recently, they further clearly illustrated that in ovarian cancer cells, ARHI contributed to the induction of autophagy by down-regulating the epidermal growth factor receptor, inhibiting PI3K and Ras/MAPK signaling and activating the FOXo3a-mediated induction of Rab7." (PMID 27825125, 2016). "EGFR expression and gene status have not been thoroughly investigated in BOTs as it has in ovarian carcinomas." (PMID 26870997, 2016). "Despite the importance of AREG and EGFR in ovarian tumorigenesis, whether SPRY2 is regulated by AREG and whether SPRY2 is involved in ovarian cancer progression are still unknown." (PMID 27835572, 2016). "EGFR is known to be highly expressed in the majority of ovarian cancers, but phase II/III trials of EGFR inhibitors have not shown favorable clinical outcomes among unselected cohorts of ovarian cancer patients, or among any subgroups thus far identified." (PMID 26437224, 2015). "The concurrent activation of multiple signaling pathways, including EGFR, PI3/AKT, MEK/ERK and JAK/STAT3, appears to be more common in ovarian cancer and raises an important question about the involvement of these signaling pathways in the development of drug resistance." (PMID 25928246, 2015). "SPINK1 has been reported previously to stimulate proliferation through activation of EGFR signaling as a putative novel EGFR ligand in several other tumor types, but this phenomenon has not been examined in ovarian cancer models." (PMID 26437224, 2015). "Taken together, our results suggest that resveratrol and the derivatives, acetyl-resveratrol and polydatin, have antigrowth activities against 3D cell aggregates of ovarian cancer cell lines regardless of the level expression of EGFR and Her-2." (PMID 26617640, 2015). "EGFR and IL-6R signaling cross-talk through JAK2/STAT3 to mediate EMT in ovarian carcinomas; activated STAT3 in high-grade ovarian carcinomas may occur directly through activation of EGFR/IL-6R or indirectly through induction of IL-6R signaling." (PMID 25566498, 2014). "We have also determined that crosstalk can occur bidirectionally between EGFR and PAFR, suggesting that EGF-induced PAF production could result in positive feedback that acts on the PAF-receptor to promote ovarian cancer progression." (PMID 24721622, 2014). "The transactivation of EGFR through other G-protein coupled receptors (GPCR) is an important signaling pathway for the induction of both mitogenic and motogenic effects, suggesting a mechanism for the proliferative effects of PAF in ovarian cancer cells." (PMID 25261977, 2014). "Previous studies showed that EGFR regulates AKT and ERK1/2 activity in ovarian cancer." (PMID 24816687, 2014). "Of note, no ovarian cancer patients within any stratum exhibited ALK rearrangement, BRAF, EGFR, or KIT mutations." (PMID 25593979, 2014). "Targeting these proinflammatory chemokines may be a promising therapeutic strategy for ovarian cancer with abundant TNF and EGFR activation patterns." (PMID 23800251, 2013). "Real-time PCR and immunohistochemical analysis showed that the levels of EGFR mRNA and protein were increased in non-mutated and BRCA1-mutated ovarian cancer compared with their adjacent normal tissue." (PMID 24321281, 2013). "Thus augmentation of proinflammatory chemokines CXCL1/2, by potentiating NF-κB activation through EGFR-transactivated Akt, contributes to CXCR2-driven ovarian cancer progression." (PMID 24376747, 2013). "Impaired activation of the EGFR and Erk1/2 signaling pathways due to HE4 knockdown could be restored in ovarian carcinoma cells using HE4-containing medium." (PMID 23894390, 2013). "The anti-EGFRvIII and anti-EGFR antibody guided vectors delivered the DNA constructs for DNase1, DNase1L3, DNase2, DFFB into the nuclei of the human EGFRvIII and EGFR over-expressing ovarian cancer cells from ascites and cultures." (PMID 24587967, 2013).
ovarian carcinoma (continued). "Targeting these proinflammatory chemokines may support a promising therapeutic strategy for inflammatory ovarian cancer with abundant TNF and EGFR activation pathways." (PMID 23800251, 2013). "Based on the synergistic increase of CCL20 and CXCL8 in response to EGF and TNF, CCL20 and CXCL8 may be the dominant chemokines found in ovarian cancer cells with abundant TNF, and/or activation of the EGFR." (PMID 23800251, 2013). "In ovarian cancer cells that exhibit resistance to cisplatin therapy, NCX-4016, a nitro-derivative of aspirin, has been reported to inhibit effectively the EGFR signaling involving Y845 and Y992 phosphorylation of the receptor, and the activation of Akt and STAT3." (PMID 23702846, 2013). "Indeed, cancerous ovaries of hens show very similar patterns of expression of tumor-related genes compared with those in women, and high cross-reactivity and expression of biomarkers such as CA125, EGFR, and ERBB-2 for human ovarian cancer." (PMID 22496782, 2012). "EGFR/Akt pathway contributes to the aggressive progression in ES-2 peritoneal metastasis model and effective delivery into ascites of IHL-305 was thought to useful treatment for ovarian cancer with peritoneal metastasis." (PMID 23046546, 2012). "The targeting of multiple signaling pathways such as VEGFR, EGFR, IL-6R-JAK-STAT3/NF-κB, PI3K/AKT/mTOR, and ABC drug transporters in ovarian cancer may be an auspicious start to favourable PFS and OS outcomes." (PMID 22481932, 2012). "Irrespective of the prospects for molecular targeting of EGFR RTKs in ovarian cancer, resistance to EGFR inhibitors and unwanted adverse events in ovarian and non-ovarian tumors are major clinical concerns that need to be circumvented." (PMID 22481932, 2012). "Vandetanib (ZD6474, ZactimaTM), which inhibits VEGFR2 and EGFR signaling, had no clinical activity in monotherapy in recurrent ovarian cancer." (PMID 23109896, 2012). "In order to study the interaction of these pathways, ERK inhibitor (PD98059), PI3K inhibitors (LY294002, wortmannin), Akt inhibitor (A6730), and EGFR inhibitor (erlotinib) as well as the corresponding siRNAs were used to treat MDA-MB-231 cells, and ovarian cancer OVCAR-3 and SKOV-3 cells." (PMID 22534171, 2012). "Hence, data from the present study indicate that a complex interplay between ER-α and GPR30 contributes to low concentrations of BPA activity in GC-1 cells by activating EGFR-ERK transduction pathways, similar results for atrazine in ovarian cancer cells." (PMID 21813366, 2011). "The receptor tyrosine kinases (RTKs), including EGFR, ERBB2, PDGFR, VEGFR and MET, are activated in subsets of ovarian cancer, suggesting that these kinases might represent novel therapeutic targets." (PMID 21962244, 2011). "In contrast, clinical studies with EGFR blocking drugs in advanced ovarian cancers have shown only limited efficacy but in the majority of these trials, EGFR positivity was not analyzed as a selection criterion." (PMID 21756326, 2011). "Therefore, we explored the possibility of an interaction between EGFR, COX-2 and CRM1 in ovarian cancer." (PMID 21756326, 2011). "Sensitivity to vandetanib in the MPM cell lines also fell within the range of IC50 values previously reported for other carcinoma cell lines, including pancreas, breast, colon, gastric and ovarian cancer cells with functional EGFR but lacking VEGFR-2." (PMID 21970874, 2011). "The mechanisms of EGFR activation and particularly the intracellular transactivation in ovarian cancer are not yet fully elucidated." (PMID 21756326, 2011). "To further establish the efficacy and specificity of this targeting method, we established a model using ovarian cancer cell lines either positive or negative for expression of EphA2 and positive for expression of EGFR." (PMID 20064265, 2010). "In ovarian cancer cell lines challenged with LPA, we observed only weak transactivation of EGFR." (PMID 20074357, 2010).
ovarian carcinoma (continued). "Aberrant EGFR and HER2 expression was reported in ovarian carcinomas." (PMID 20049170, 2010). "While the amount of information regarding EGFR-mediated signaling is considerable, current data provides little insight for the lack of efficacy of anti-EGFR agents in ovarian cancer." (PMID 20037743, 2010). "Currently, there are no full reports of clinical trials for ovarian cancer with other anti-EGFR antibodies such as zalutumumab (HuMax-EGFr) and nimotuzumab (BIOMAbEGFR)." (PMID 20037743, 2010). "Previous in vivo studies in lung cancer showed that decreased EGFR level might be involved in the antiproliferative effect of GHRH antagonists, but it hasn't been reported in ovarian cancer cell lines by JMR-132 treatment." (PMID 20509930, 2010). "Selection of ovarian cancer patients with EGFR amplifications, increased pHER2, and low expression of HER 3 ratios may represent the selected few that may respond to EGFR inhibitors." (PMID 20069122, 2010). "In addition, JMR-132 treatments decreased significantly the epidermal growth factor receptor (EGFR) level and the phosphorylation of Akt (p-Akt), suggesting that JMR-132 inhibits the EGFR-Akt pathway in ovarian cancer cells." (PMID 20509930, 2010). "Although erlotinib (EGFR tyrosine kinase inhibitor) does not have any relevant single-agent activity in ovarian cancer, combined VEGF and EGFR inhibition is currently under investigation." (PMID 19002176, 2009). "Based on our findings and combined with data from the literature it can be concluded that EGFR/HER2-neu directed molecular treatments could benefit and should be investigated in one fourth of all invasive epithelial ovarian cancers." (PMID 18182111, 2008). "Epidermal growth factor receptor (EGFR) and HER-2/neu are frequently expressed in ovarian cancer but their prognostic value remains unclear." (PMID 18628764, 2008). "Treatment with agents directed against these proteins may enhance chemotherapy-induced cell death The prognostic significance of EGFR and HER-2/neu has been extensively studied in ovarian cancer, but remains unclear." (PMID 18628764, 2008). "Clinical studies involving tyrosine kinase inhibitors in ovarian cancer are ongoing and in the one study that has been published to date, analysis of EGFR gene copy number by FISH or CISH was not included." (PMID 18182111, 2008). "Studies with these molecules have not been reported in ovarian cancer despite the high rate of immunohistochemical EGFR positivity." (PMID 18182111, 2008). "No trials have yet demonstrated the efficacy of EGFR TKIs in ovarian cancer." (PMID 40364160, 2025). "Moreover, naloxone failed to influence p-EGFR level, though it reversed fentanyl-mediated phosphorylation of EGFR and reduced the migratory ability of ovarian cancer cells." (PMID 39861181, 2025). "Interestingly, our recent study also revealed that monensin effectively inhibited EGFR and tumor grow in human ovarian cancer, however no inhibition to IGF1R was observed." (PMID 36896461, 2023). "Consequently, we hypothesized that MICALL2 may promote EGFR-signaling activation and MMP9 expression in ovarian cancer cells." (PMID 38203692, 2023). "Additionally, when coupled with the epidermal growth factor receptor (EGFR) - targeting antibodies, sgPLK1-cLNPs was systemically and selectively disseminated to reach metastatic ovarian cancer cells allowing ~80% of gene editing, significant tumour growth inhibition, and 80% increase in survival." (PMID 37545694, 2023). "The combination of pan-EGFR inhibitor neratinib was synergistic with niraparib in ovarian cancer cell lines as well, leading to the ongoing clinical trial evaluating the combination in patients with platinum-resistant, BRCA1/2 wild-type ovarian cancer (NCT04502602)." (PMID 37430137, 2023).
ovarian carcinoma (continued). "Therefore, we speculated that MYC, EGFR, and CCND1 might enhance resistance to platinum chemotherapy in ovarian cancer." (PMID 35739532, 2022). "In line with this, the dual EDNRA/B inhibitor macitentan blocked metastatic progression of ovarian cancer cells, and zibotentan, a specific EDNRA inhibitor showed synergistic effects on apoptosis and inhibition of ovarian cancer cell invasion, when used in combination with EGFR inhibitors." (PMID 35625966, 2022). "Several genes found in our analysis have previously been described as biomarkers of ovarian cancer or potential therapeutic targets, including genes from the ITGA and ITGB superfamily, laminins, fibroblast growth factors, collagens, insulin growth factors, EGFR, FN1, EPHA2, TNC, SPP1, and VTN." (PMID 36352420, 2022). "Therefore, it was speculated that MYC, EGFR, and CCND1 might affect the survival of ovarian cancer patients by mediating chemoresistance-related pathways." (PMID 35739532, 2022). "Additionally, its efficiency to target EGFR has been shown using the GE11 peptide-modified polymersomal doxorubicin, which has emerged as an advanced alternative to the current Lipo-Dox treatment in EGFR over-expressing ovarian cancers." (PMID 36004905, 2022). "Additionally, we observed that protein expression of MYC, EGFR, and CCND1 was notably increased in cancer tissues of ovarian cancer patients based on data from Human Protein Atlas, suggesting their important functional significance in ovarian cancer." (PMID 35739532, 2022). "A recent study has identified that MYC, EGFR, and CCND1 can be amplified on extrachromosomal DNA (ecDNA) in different tumor cell lines, which may provide novel insight into identification of the mechanism of ovarian cancer progression." (PMID 35739532, 2022). "Thus, a method for blocking the EGFR and STAT3 pathways in ovarian cancer needs to be developed." (PMID 34369236, 2021). "However, EGFR inhibitor treatment failed to achieve sufficient clinical benefit ovarian cancer patients when used a single agent or in combination with chemotherapy in ovarian cancer." (PMID 34369236, 2021). "However, we also demonstrated that EGFR knockdown could increase STAT3 phosphorylation in HO8910 and OVCAR-3 ovarian cancer cells." (PMID 34369236, 2021). "The EGFR‐COPA/GRN/HBEGF pairs were expressed at higher levels in the metastatic tumors than those in the primary tumors, suggesting that these cell‐to‐cell connections might be important for ovarian cancer metastasis." (PMID 34459128, 2021). "It is also possible that the high mutational burden commonly seen in ovarian cancer leads to constitutively active ERK, which may not respond to EGFR blockade upstream of ERK." (PMID 32231055, 2020). "Conversely, intrinsic resistance to cetuximab could not be resolved by sensitizing ovarian cancer cells with anti-EGFR TKIs." (PMID 31546690, 2019). "So far, anti-EGFR targeting in ovarian cancer has not reached sufficient clinical benefit." (PMID 31546690, 2019). "Thus, in this paper, it was investigated whether CHAG inhibited the development of ovarian cancer cells via abrogation of activation of EGFR and EGF/EGFR mediated signaling cascades." (PMID 29510732, 2018). "In conclusion, our results and the current literature indicate that EGFR may not be a robust or generally applicable prognostic immunohistochemical marker for ovarian cancer patients." (PMID 28740577, 2017). "Furthermore, an EGFR inhibitor, erlotinib, reversed the effects of GALNT6 overexpression on malignant behavior of ovarian cancer cells, indicating that EGFR is a key mediator of GALNT6 effects on ovarian cancer cells." (PMID 28388560, 2017). "The progression of colon, lung, breast, head and neck, prostate and ovarian cancers have all been reported to be mediated, at least in part, by GPCR-EGFR crosstalk, indicating that combined GPCR and EGFR inhibition could induce more pronounced clinical responses." (PMID 27187360, 2016).
ovarian carcinoma (continued). "However, the activated EGFR was not involved in NF-κB activation in MyD88-positive ovarian cancer cells." (PMID 27708225, 2016). "Although EGFR nuclear translocation can be expected to activate DNA-PK as a counter measure to DNA damage due to quercetin and PAC-9 treatment, immunofluorescence microscopy analysis revealed downregulation of DNA-PK in ovarian cancer cells exposed to quercetin aglycone or PAC DP-9." (PMID 25776829, 2015). "The purpose of this study was to investigate and compare any potential antigrowth effects of resveratrol and two of its derivatives, acetyl-resveratrol and polydatin, on 3D cell aggregates of the EGFR/Her-2 positive and negative ovarian cancer cell lines SKOV-3 and OVCAR-8, respectively." (PMID 26617640, 2015). "Oxygenation of human A2780 ovarian carcinoma tumors, that are negative for EGFR, xenografted onto the chorioallantoic membrane of chicken embryos was studied following treatment with the anti-angiogenic tyrosine kinase inhibitors (TKIs) axitinib, sunitinib or erlotinib." (PMID 25758612, 2015). "However, the PKC activator PMA activated the phosphorylation of ERK, and the phosphorylation of ERK was inhibited by PKC inhibitor GF109203X, indicating that PAF activates ERK, the downstream target of EGFR, via PLCβ-dependent PKC and MMP-mediated EGFR pathways to promote ovarian cancer progression." (PMID 25261977, 2014). "In our in vitro and in vivo studies, we demonstrated that EGFR and PAFR were overexpressed in ovarian cancer cell lines, which led us to speculate that simultaneously targeting PAFR and EGFR may be a more effective therapeutic strategy than targeting either signaling pathway alone." (PMID 24886678, 2014). "In the current study, we evaluated the relationship between GPR30 expression and patient clinicopathological factors by immunohistochemistry in ovarian cancer specimens, and evaluated whether GPR30 mediates Akt activation via the EGFR, leading to a poor prognosis for ovarian cancer patients." (PMID 23163984, 2012). "Therefore, the molecular targeting of multiple signaling pathways such as EGFR, VEGFR, HIF-1, and PI3K/PTEN/AKT/mTOR may improve responses in recurrent and resistant ovarian cancers." (PMID 22481932, 2012). "However, clinical trials have not or just partially shown benefit to ovarian cancers treated with EGFR, ERBB2, or PDGFR inhibitors." (PMID 21962244, 2011). "Similarly, only a mild effect on ovarian cancer viability were detected after gefitinib-mediated EGFR inhibition and the cell death did not correlate with baseline EGFR tyrosine phosphorylation, in spite of strong EGFR expression in many ovarian cancers." (PMID 21962244, 2011). "Furthermore, the EGFR small molecular inhibitors gefitinib and erlotinib inhibited EGFR-mediated AKT and MAPK phosphorylation and decreased tumor cell proliferation in some ovarian cancer cell lines and tumor xenograft models." (PMID 21962244, 2011). "Similarly, vandetanib, a small molecule inhibitor of VEGFR and EGFR signalling, did not demonstrate significant clinical benefit in recurrent ovarian cancer." (PMID 21364581, 2011). "To date, the exact frequency of EGFR expression in ovarian cancer is not clear." (PMID 21756326, 2011). "However, the molecular mechanisms linking GHRH antagonists to the EGFR pathway in ovarian cancer cells were not well established." (PMID 20509930, 2010). "Reports of inhibition of EGFR with tyrosine kinase inhibitors (TKI) [e.g. gefitinib (Iressa)] and monoclonal antibodies (e.g. cetuximab) have demonstrated that silencing of receptor activity increases chemosensitization of tumor cells including ovarian cancer cells." (PMID 20064265, 2010). "It has been proposed that constitutive STAT3 activation can result from aberrant EGFR signalling and a significant correlation between high overall levels of P-STAT3 expression and overexpression of EGFR and HER-2/neu has been reported in ovarian cancer specimens." (PMID 19088723, 2009).